INS (insulin)
Diseases named in the same sentence as INS in open-access papers (continued):
Sharing a sentence is not in itself a finding about the gene and the disease.
diabetes (continued). "Treatment of diabetes is centered around the delivery of insulin for all T1D patients because external insulin is necessary to maintain glycemic control and prevent ketoacidosis." (PMID 38509342, 2024). "Limited data support oral agents after relapse in 6q24-TND and for thiamine improving glycemic control and reducing/eliminating insulin requirement in SLC19A2-diabetes." (PMID 39025920, 2024). "Relevant studies have now well demonstrated that these two forms of diabetes commonly share an enhanced ER stress in pancreatic β-cells that negatively impacts insulin secretion." (PMID 38966213, 2024). "PTx and IT are procedures aimed at restoring insulin production and improving blood glucose management in individuals with brittle diabetes." (PMID 39767759, 2024). "RSV has demonstrated potential in managing blood glucose levels and mitigating diabetes, which is supported by the findings of clinical trials showing its effectiveness in improving insulin sensitivity." (PMID 39593801, 2024). "Diabetes is characterized by elevated blood glucose levels due to insufficient insulin secretion by pancreatic β cells or increased insulin resistance to glucose." (PMID 39572023, 2024). "Alzheimer’sdisease (AD) is a complex neurodegenerativeprocess, also considered a metabolic condition due to alterationsin glucose metabolism and insulin signaling pathways in the brain,which share similarities with diabetes." (PMID 39007352, 2024). "Patients with higher TWAG tended to have higher BMI, heart rate, APS III, creatinine, mean insulin dose, diabetes, and RRT." (PMID 38413682, 2024). "The widespread dissemination and adoption of continuous glucose monitoring (CGM) and automated insulin delivery (AID) systems have completely changed the daily lives of patients with diabetes, improving the quality of life of both children and their families." (PMID 38894740, 2024). "They demonstrated only a transient increase in glucose variability and no changes in glycemic control measures during RF, although subjects with insulin-treated diabetes showed greater glucose excursions than the other medication groups." (PMID 39203800, 2024). "Diabetes mellitus (DM), a metabolic disease, results from chronic increased blood glucose (hyperglycemia) due to defect in insulin secretion, the function of insulin or both." (PMID 39474345, 2024). "Currently, some strategies are being applied for diabetes mellitus treatment, such as diet, exercise, various oral antidiabetic drugs, and insulin therapy." (PMID 39723093, 2024). "We can achieve it using both relatively new drugs like the phlazines or the still-investigational DPP4 inhibitors, but the long-known diabetes drugs like insulin or metformin will work just as well here." (PMID 38672121, 2024). "Diabetes mellitus (DM) is a group of metabolic diseases characterized by chronic hyperglycemia, resulting from defects in insulin secretion, insulin action, or both." (PMID 38794235, 2024). "While insulin continues to be the mainstay of diabetes therapy, technological advancements in insulin delivery have significantly improved the management of all types of diabetes." (PMID 39211732, 2024). "Diabetes mellitus (DM), a chronic and multifaceted metabolic disorder, is represented by sustained hyperglycemia arising from factors such as insulin resistance, inadequate insulin secretion, or a combination thereof." (PMID 39064398, 2024). "The information collected were age, gender, diabetes medications, glycemic indices, lipid profile, fasting insulin, homeostatic model assessment for insulin resistance, and body mass index." (PMID 39429295, 2024). "Combining the results of molecular docking and previous reports, we found that berberine was reported to be more involved in diabetes and insulin resistance among the top 10 compounds ranked by affinity." (PMID 39285464, 2024).
diabetes (continued). "In contrast rates of fetal death in women with insulin treated diabetes were 26 per 1000 births accounting for an RR of 4.24 [2.11–8.53] and dropped to 7.4 (per 1000 births) still accounting for a significant increased RR of 3.27 [1.04–10.3]." (PMID 38958733, 2024). "The UK National Diabetes Inpatient Audit (NADIA) highlighted 40% of insulin-treated inpatients experienced one or more insulin error." (PMID 39666732, 2024). "Rarely, brittle diabetes can be secondary to an underlying medical condition, such as MSUD, causing disruption in insulin sensitivity or glucose utilization." (PMID 39347258, 2024). "The most commonly studied populations were non-insulin-treated patients, those with moderately controlled diabetes (HbA1c > 7%), newly diagnosed patients (< 1 year), and adults with T2DM." (PMID 39639901, 2024). "They found that there is an inverse association between diabetes and ALS risk (OR 0.66), especially in non-insulin-dependent patients." (PMID 38791099, 2024). "In diabetes, decreased insulin, elevated saturated fatty acids, and carbohydrate surges (e.g., glucose and fructose) collectively upregulate APOC3, increasing TG levels and TRLs accordingly." (PMID 39684468, 2024). "Although significant advancements in insulin therapy for children with type 1 diabetes mellitus (T1DM) have allowed many patients to reach normal or just slightly reduced final height, anomalies of growth often persist." (PMID 38712328, 2024). "Mice models with homozygous deletions of the IRS1 or IRS2 genes display peripheral insulin resistance and diabetes, along with compromised insulin secretion due to disrupted PI3K/AKT signaling." (PMID 39125938, 2024). "This nationwide study of MA beneficiaries with diabetes between 2013 and 2018 examined if OOPC is associated with reduced insulin adherence." (PMID 36992575, 2024). "SU is elevated in metabolic syndrome (MS) and diabetes as a consequence of insulin resistance and the effects of insulin to reabsorb more urate resulting in reduced urinary urate excretion." (PMID 39618812, 2024). "Type 2 diabetes mellitus (T2DM) is a chronic metabolic disease caused by insulin resistance (IR) and insufficient insulin secretion." (PMID 39720247, 2024). "Additional studies have been limited to therapeutic errors involving single medication categories, such as only insulin or metformin, which precluded comparisons among diabetes medication categories." (PMID 39300573, 2024). "Glucagon-like peptide 1 (GLP-1) receptor agonists (GLP-1 RAs) are primarily used in diabetes management to enhance insulin release by stimulating GLP-1 receptors in the pancreas." (PMID 39677183, 2024). "Since beta-cell mass (BMC) acts directly in the physiopathology of diabetes, it has been proposed as an alternate approach to monitor the progression of type I diabetes in accompaniment to insulin-producing cell activity." (PMID 38355744, 2024). "Participants had an average diabetes duration of roughly 12 years, and approximately 39% of the sample was using insulin at the time of data collection." (PMID 38671288, 2024). "Diabetes mellitus consists of several metabolic disorders that affect insulin production, the action of insulin, or both." (PMID 38686006, 2024). "One such disease is diabetes mellitus, a chronic health condition affecting millions of people all over the world, in which the production and/or effectiveness of insulin are compromised." (PMID 39619638, 2024). "She developed diabetes requiring insulin treatment after the transplantation procedure, despite only a brief course of steroids for immunosuppression, with no notable change in the lipodystrophy phenotype after approximately 2 years from the surgery." (PMID 38271099, 2024). "These issues included elevated stress levels, worries about access to insulin and diabetes supplies, and transitions in DM management between adolescents and their parents/guardians." (PMID 39867016, 2024).
diabetes (continued). "Our results showed that diabetes increased blood glucose levels, decreased insulin and sex hormone levels, induced testicular oxidative stress and apoptosis, and reduced sperm parameters compared to the control." (PMID 39391856, 2024). "A 52-year-old donor was undergoing insulin treatment to control type 2 diabetes mellitus, but her sample had similar characteristics to those of the other donors with this diagnosis." (PMID 39479185, 2024). "Insulin vesicles undergo a complex functional maturation process that is required for proper secretion of insulin and this process is dysregulated in diabetes." (PMID 39190030, 2024). "Diabetes mellitus (DM) is a significant global public health issue, characterized by chronic metabolic dysregulation due to insulin resistance and inadequate insulin secretion." (PMID 39902163, 2024). "The study involved 141 patients with diabetes who recently had a myocardial infarction (MI) and were being treated with insulin and/or a sulphonylurea before the hospital admission." (PMID 39120245, 2024). "Glucocorticoids can induce gluconeogenesis and inhibit insulin sensitivity, leading to steroid-induced diabetes." (PMID 39121259, 2024). "These essential fatty acids play crucial roles in diabetes due to their involvement in various metabolic pathways and their influence on inflammation, lipid metabolism, insulin resistance, glucose homeostasis, and insulin signaling." (PMID 39355538, 2024). "C-peptide as a marker of insulin requirement is commonly measured in patients with type 1 diabetes mellitus, but low endogenous insulin production commonly remains unchecked in most patients with type 2 diabetes mellitus." (PMID 38654804, 2024). "Advanced treatment options, such as whole-pancreas transplantation and islet transplantation, aim to restore insulin production and improve glucose control in selected patients with diabetes." (PMID 39767759, 2024). "Some researchers argue that excessive glucagon expression may play a more crucial role in diabetes development than insulin deficiency, as accumulation of glucagon could potentially play a more important role in the progression of diabetes compared to insufficient insulin production." (PMID 39641365, 2024). "Diabetes mellitus is a condition resulting from a defect in insulin secretion, leading to the buildup of Glu." (PMID 39583130, 2024). "Type 2 diabetes mellitus (T2DM), one of the chronic metabolic disorders, causes a disorder in insulin secretion, leading to hyperglycemia." (PMID 38524632, 2024). "Hypertension, peripheral neuropathy, nephropathy, ≥10 year’s duration of diabetic mellitus, insulin use and poor adherence to diabetes mellitus medications were among the factors significantly associated with proliferative diabetic retinopathy." (PMID 38728350, 2024). "It was the culmination of this scientific effort that led to the development of insulin as a drug, which can now be purified, stabilized, and injected, thus making a decisive contribution to the treatment of people with diabetes mellitus." (PMID 38457064, 2024). "Diabetes mellitus (DM) with hyperglycemia is the consequence of impaired insulin secretion and insulin function or both of them." (PMID 39011434, 2024). "Insulin pumps have transformed the way diabetes is managed by providing a more accurate and individualized method of delivering insulin, in contrast to conventional injection routines." (PMID 39065641, 2024). "Diabetes is a chronic, metabolic disease characterized by elevated levels of blood glucose (hyperglycemia), which eventually results in alterations in insulin signaling, leading ultimately to insulin resistance and chronic inflammation." (PMID 38963109, 2024). "Insulin resistance is considered to be an early defect in the development of diabetes and metabolic diseases, where impairment in insulin action predates other metabolic abnormalities." (PMID 38961153, 2024).
diabetes (continued). "Type 2 diabetes mellitus (TD2M) is a chronic metabolic disease characterized by impaired insulin action, termed insulin resistance." (PMID 39590817, 2024). "Most publications included individuals with diabetes, often using meal announcements and/or insulin boluses accompanying meals." (PMID 38264192, 2024). "The average duration of diabetes was 4.8 (SD 2.9) years; 4 (67%) of the 6 participants were using an insulin pump." (PMID 38713496, 2024). "Chronic bad chest, depression, and diabetes controlled with insulin or equivalent were reported by between about 8% and 11% of caregivers." (PMID 38373905, 2024). "In terms of diabetes, the patient was put on basal-bolus insulin regimens and received therapeutic education sessions on the need for follow-up and functional insulin therapy." (PMID 39759658, 2024). "These peptides can also improve glucose metabolism and insulin sensitivity, aiding in the management of diabetes and other metabolic disorders." (PMID 39057043, 2024). "On the other hand, finding insulin levels within the reference range or above in a patient with diabetes indicates insulin resistance and an exciting potential for diabetic remission after removing the factor(s) causing insulin resistance." (PMID 38539988, 2024). "Diabetes mellitus (DM) is a group of metabolic diseases characterized by chronic hyperglycemia due to disturbances in insulin secretion, insulin action in the form of resistance, or a combination of these two." (PMID 39337594, 2024). "It was observed that only the diabetes group had decreased insulin levels, and the administration of silibinin in both doses increased insulin levels (p < .05)." (PMID 38726421, 2024). "Blood sugar regulation: Cinnamon has been studied for its potential to help regulate blood sugar levels and improve insulin sensitivity, making it potentially beneficial for individuals with diabetes." (PMID 39479640, 2024). "The treatment of diabetes encompasses various methods, including IT, continuous glucose monitoring, insulin pumps, and pancreas transplantation." (PMID 38669398, 2024). "Such systems also include alerts or alarms notifying individuals about various situations, such as high or low glucose levels, low battery of diabetes management devices, and low insulin storage." (PMID 38846748, 2024). "Diabetes is a metabolic disorder marked by the body’s failure to produce insulin (type I diabetes or insulin-dependent diabetes) or effectively utilize insulin (type II/insulin-resistant)." (PMID 39338610, 2024). "Diabetes mellitus, particularly type 2 diabetes, is a chronic metabolic disorder characterized by persistent hyperglycemia due to impaired insulin secretion, insulin resistance, or a combination of both." (PMID 39835082, 2024). "The keywords used were SGLT-2 inhibitors, Type 1 Diabetes Mellitus, automated insulin delivery systems, and diabetic ketoacidosis." (PMID 38396657, 2024). "The implementation of binary solvent systems has particularly revolutionized diabetes management through smart insulin delivery platforms." (PMID 39597358, 2024). "This approach has also been proven to be effective in improving therapeutic adherence, as it enhances awareness and acceptance of the diabetes condition, leading to better glycemic control and more consistent insulin administration." (PMID 39334618, 2024). "Insulin is an essential drug in the treatment of diabetes, often necessary for managing hyperglycemia in type 2 diabetes mellitus (T2DM)." (PMID 38559691, 2024). "In particular, it has demonstrated significant effects on obesity and diabetes, including weight reduction, improved insulin sensitivity and lowered blood glucose levels, alleviated diabetes-related cognitive impairments, and retinopathy." (PMID 39238846, 2024).
diabetes (continued). "The ZO rats exhibited lower glucose levels but the highest insulin levels among all groups, indicating phenotypic obesity with insulin resistance and a less developed stage of diabetes, consistent with previous findings." (PMID 39452068, 2024). "A few participants were already taking non-insulin adjuncts for diabetes, including metformin, empagliflozin and semaglutide." (PMID 38799027, 2024). "Central to this condition is insulin, which plays a pivotal role in regulating glucose levels in the body by aiding glucose uptake and storage in cells, and what happens to diabetes?" (PMID 38542928, 2024). "T1International and its global community of activists have advocated for the past decade for cost-reductions of insulin and other diabetes supplies at the manufacturer level, calling for the rights of patients over unrestricted profits." (PMID 38711747, 2024). "Our objective was to compare two types of insulin pumps in the treatment of type 2 diabetes mellitus (T2DM), using continuous glucose monitoring (CGM) metrics and profiles." (PMID 38599884, 2024). "Elevation of plasma glucose and reduction of plasma insulin in diabetic control rats are indicator to success of STZ as a model in induction of diabetes in rats." (PMID 38528644, 2024). "This study showed that 12 patients had spontaneous resolution of hypoglycaemia, with five patients having progression to diabetes with insufficient insulin secretion." (PMID 39153498, 2024). "This can be explained by the fact that those who are genetically inclined to diabetes develop type 1 diabetes sooner since weight gain increases insulin resistance." (PMID 39104999, 2024). "Our results not only validated the upregulated expression of NUDT12, but also revealed its involvement in insulin signaling and diabetes-related pathways through enrichment analysis." (PMID 38464965, 2024). "An intelligent, technically competent, and self-motivated patient with a good grasp of the fundamentals of diabetes self-care would be the best candidate to begin insulin pump therapy." (PMID 39065641, 2024). "The sequence of porcine insulin differs by only a single amino acid from that of human insulin and, moreover, porcine insulin was administered to treat diabetes successfully for nearly a century before the introduction of recombinant human insulin." (PMID 38464515, 2024). "Different types of questionnaires are used in diabetic patients to assess the patient’s perception regarding insulin treatment, diabetes-related emotional distress, and PIR and to identify the causes of resistance to initiating insulin therapy." (PMID 39453515, 2024). "High blood glucose levels in individuals with diabetes are managed through a combination of insulin injections, daily oral hypoglycemic agents, exercise, and diet." (PMID 38800472, 2024). "With the suspicion of an inflammatory or infectious complication of diabetes, she was hospitalized with constant rate infusion of insulin, and empirical ampicillin sulbactam was started." (PMID 38249564, 2024). "In Egypt, effective usage of insulin remains a challenge due to insufficient knowledge of insulin and diabetes management, leading to errors in insulin therapy." (PMID 38594659, 2024). "Carbohydrate intake is particularly important in diabetes management, as it is the main source of glucose and the primary factor in insulin secretion." (PMID 39125422, 2024). "Branched-chain amino acids (BCAAs), which include valine, leucine, and isoleucine, have been found to be closely related to insulin and diabetes more than 70 years ago." (PMID 39635431, 2024). "Encouragingly, FDA-approved nanotechnology-based formulations and pulmonary insulin delivery systems have demonstrated clinical success, highlighting the potential of nanotechnology in diabetes care." (PMID 39771551, 2024).